TNF (tumor necrosis factor)
Diseases named in the same sentence as TNF in open-access papers (continued):
Sharing a sentence is not in itself a finding about the gene and the disease.
infection (continued). "BR15 infection induced a modest but statistically significant increase in TNF-α expression (p < 0.05) and a significantly higher expression of IFN-β1, IL-1β, IL-6, and IL-10, as well as the chemokines CCL2 (MCP-1), CCL5 (RANTES), and CXCL8 (IL-8), compared to MR766-infected cells." (PMID 40732762, 2025). "Additionally, these T cells potentiate IFNγ production by natural killer (NK) cells, likely via TNFα and interleukin (IL)-12 produced during infection." (PMID 40667022, 2025). "LC patients showed slightly increased secretion of IL-1β, IL-6, TNF-α, GM-CSF and G-CSF, raising the possibility that other pro-inflammatory cytokines may also be disturbed, as observed by others 8 months after infection." (PMID 40566632, 2025). "M1 macrophages are pro-inflammatory cells that, in response to infection or inflammation, release cytokines like interleukins (IL-1β, IL-6, IL-12, and IL-23) and tumor necrosis factor α (TNF-α).It mainly plays the role of promoting inflammation and causing tissue damage." (PMID 40599770, 2025). "Notably, JUP deficiency resulted in significantly lower levels of IL-1rα, IL-12 (p70), MIP-1α, MIP-1β, RANTES, and TNF-α at 15 h post-infection, compared to siCN-treated cells, supporting the importance of JUP in RSV-induced cellular responses." (PMID 40431638, 2025). "Consistent with the severe airway inflammation observed via histopathology analysis, sublethal infection with wild-type K7 boosted the secretion of the inflammatory cytokines TNF-α, IL-6 and IL-1β, whereas the levels of these cytokines were significantly reduced by IFA treatment." (PMID 39761301, 2025). "For TNF-α, the difference was more significant at 3 h post-infection." (PMID 40818988, 2025). "During this period, the immune system is highly active, with massive proliferation of inflammatory cells (mainly granulocytes) and release of large amounts of inflammatory factors such as tumor necrosis factor-alpha and interleukins (IL-1, IL-6) to fight infection and injury." (PMID 40771209, 2025). "During the acute phase of infection, a robust immune response is triggered, characterized by the release of pro-inflammatory cytokines such as interleukin-6 (IL-6), tumor necrosis factor-alpha (TNF-α), and interleukin-1β (IL-1β)." (PMID 41306980, 2025). "Tumor necrosis factor alpha (TNFα) did not significantly change after infection with SARS-CoV-2 variants, potentially due to a lack of circulating immune cells." (PMID 41157615, 2025). "In the event of infection and subsequent inflammation of the pancreas, macrophages are able to respond rapidly to PAMPs and transcribe the TNF gene, which is already in a state of readiness, to rapidly produce TNF." (PMID 40909291, 2025). "When monitoring DFUs and VLUs, a set of key parameters, such as temperature, pH, hydration, and specific inflammatory biomarkers, like cytokines (i.e., IL-6 and TNF-α) and proteases (i.e., MMPs), can be used to assess wound status, detect early signs of infection, and guide treatment strategies." (PMID 39926013, 2025). "To determine whether IL-12 or TNFα influence IFNγ production by NK cells, we treated PBMCs at the start of infection with anti-IL-12/23 p40, anti-TNFα, or both." (PMID 41452934, 2025). "In contrast, the different feeding conditions had little effect on Wgn and Grnd expression, although Wgn displayed significantly reduced levels of expression in the carcass following P. berghei infection, suggesting the potential down-regulation of TNF signaling in the carcass following infection." (PMID 40608824, 2025). "In addition, while subtype C infections result in the increase in multiple biomarkers post infection, subtype A infection is mostly defined by an increase of TNFα." (PMID 40862133, 2025). "For instance, wild-type AMs may exhibit a stronger pro-inflammatory response (such as the secretion of IL-1β and TNF-α) after infection, whereas the response of MH-S cells may be more inclined toward specific antiviral or antibacterial mechanisms." (PMID 41039310, 2025).
infection (continued). "In ART‐treated SIV‐infected macaques, expression of IFN‐γ was higher than prior to infection in both peripheral blood and gut‐derived γδ T cells, with enhanced TNF‐α production and reduction in IL‐17 expression, demonstrating a loss of Th17 phenotype and a trend toward a Th1 phenotype." (PMID 41323021, 2025). "However, the addition of CCR2 antagonists on day 28 partially restored the levels of TNF-α and IFN-γ caused by H37Ra infection, suggesting that immunosuppression was reversed." (PMID 41562082, 2025). "TNFα level peaked at 1.5 h and remained plateaued at 4 and 6 hours post infection." (PMID 40034692, 2025). "As it is well known that NF-κB mediates the induction of cytokines in monocytes and macrophages, we also used ELISA to measure the levels of TNF-α, which facilitates communication between immune cells and other cell types in the body to coordinate responses to infection or injury." (PMID 40022203, 2025). "After the first session of TPE+CVVDH, a negative correlation trend was found between IFN-γ, IL-2, IL-12 (p70), TNF-α, and parasite density, which may be due to the complex biological mechanisms triggered by infection with P. falciparum." (PMID 41552719, 2025). "PwCF have higher baseline levels of neutrophil recruitment factors including IL-6, IL-8, and TNF-α, leading to an increase in neutrophil recruitment with disputes on whether this occurs prior to infection or after the first infection." (PMID 40357395, 2025). "Moreover, clear TNF staining was observed around the blood vessels of livers 7 days after infection." (PMID 40064845, 2025). "VAP cases exhibited higher TNF-α levels and metabolic profiles indicative of anaerobic adaptation, while IL-1β elevations were primarily linked to mechanical ventilation rather than infection." (PMID 40611327, 2025). "Although unexplored in a zebrafish infection model, PI3Kδ inhibition has been reported to reduce the migration of human neutrophils in vitro and also reduces neutrophil migration towards a TNFα injection site in mouse." (PMID 40692416, 2025). "Specific next steps may include conducting pediatric trials that incorporate microbiome monitoring to better understand the impact of TNF-α inhibitors on gut microbiota and infection risks." (PMID 41329755, 2025). "We have previously shown that infection with SARS-CoV-2 P21 causes increased production of a range of pro-inflammatory cytokines in the lungs of infected WT animals at multiple time points post-infection, including IL-1β, IL-18, IL-6, TNF, IFN-γ and others." (PMID 40016339, 2025). "Finally, we compared COX-2 regulation in GFs and dermal fibroblasts (DFs) derived from healthy skin specimens and observed that infection of each cell type with F. nucleatum in the presence of TNF results in a nearly identical synergistic induction of COX-2." (PMID 40178270, 2025). "Furthermore, Mafb-deficient macrophages secreted a large amount of these cytokines upon infection with M. tuberculosis, indicating that MafB limits the secretion of TNF-α and IL-12p40 in M. tuberculosis-infected macrophages." (PMID 40906796, 2025). "In those who have experienced prior COVID-19 exposure, either via infection or immunisation, the immune system may remain primed as demonstrated by sustained elevations of inflammatory markers IL-6 and TNF-α for up to 12 months post-infection." (PMID 41303146, 2025). "Thus, kinases as essential regulators of glucose metabolism as well as critical immune mediators during this infection such as interferons, tumor necrosis factor-alpha and transforming growth factor beta have been illustrated." (PMID 41511331, 2025). "TNF-α enhances immune regulation by promoting lymphocyte migration to infection sites." (PMID 39891135, 2025). "To determine whether this cytokine production influences infection outcome, we performed neutralization assays targeting TNF-α, TGF-β, and IL-10, followed by assessment of parasite burden." (PMID 41156732, 2025).
infection (continued). "However with the secretion of TNF, the increased levels of pIκBα were also detectable at the basal level even before MNoV_S99 infection in Ubi_K48R cells." (PMID 40395509, 2025). "In addition to reducing Infection rates, the significant reduction In proinflammatory cytokines (TNF-α, IL-1, IL-6) In the research group provides further evidence of the efficacy of the combined HPNS and probiotic Intervention." (PMID 40951884, 2025). "Conversely, patients with elevated TNF-α levels may benefit from intensified perioperative strategies, such as prolonged prehabilitation, enhanced infection prevention protocols, or alternative surgical planning (e.g., lower risk anastomoses)." (PMID 40596170, 2025). "The stimulatory activity of TcpC on IL-1β and TNFα secretion is remarkable, since bacterial numbers, which were identical between the strains at the beginning of the infection, were reduced Atc-dose dependently at the end of the culture period of 5 h due to induced TcpC expression." (PMID 41310197, 2025). "We first investigated whether the NF-κB promoter is activated during a productive infection by HAdV-C5, comparing the activation levels to those triggered by TNFα, a representative of well-known activators of NF-κB signaling." (PMID 40103806, 2025). "Cross-referencing with the KEGG and Reactome databases revealed that the infection-related pathways (IL-17, IL-10, and TNFα signaling) were significantly enriched among the downregulated genes, indicating the reduced activity of these pathways in the classical and intermediate monocytes of patients." (PMID 41280901, 2025). "In antiviral immunity, other cytokines (such as tumor necrosis factor α (TNF-α), interleukin (IL)) can enhance the inflammatory response, attract immune cells to the site of infection, promote virus clearance, and participate in the activation of adaptive immunity." (PMID 41472136, 2025). "Infection with OMP25-deficient or bvrR mutant strains (lacking OMP25 expression) leads to significantly higher TNF-α secretion in DCs, inducing DC maturation and T cell activation; this effect can be completely blocked by anti-TNF-α antibody." (PMID 41583483, 2025). "We found that TNF-α production is also essential in response to fas2Δ/Δ infection." (PMID 40138332, 2025). "This increased risk of latent TB reactivation may be explained by the role of TNF-alpha in maintaining granulomas which wall off the infection." (PMID 40236366, 2025). "Upon infection, the bladder-tissue-resident macrophages secrete chemokines to recruit neutrophils in very large numbers, and both types of sentinel cells also secrete TNF-α, allowing the neutrophils to cross the epithelial barrier." (PMID 41516024, 2025). "Moreover, the immune-related genes IL-1β and TNF-α were significantly upregulated in supplemented groups, both before and after infection, suggesting enhanced immune readiness and responsiveness." (PMID 41188425, 2025). "Certain immune cells within vulnerable populations may generate TNF-α in response to external conditions and infection, IL-1β, IFN-α and IL-6, thereby promoting the production of IL-23 by dendritic cells." (PMID 40540498, 2025). "Proinflammatory cytokine TNF-α significantly changed after infection." (PMID 40663568, 2025). "Protein levels of CCL4, IL-1β, and TNF-α correlated with expression of the interferon signaling module in BECs with increased protein levels after RV-16 infection correlating with increased expression post-infection." (PMID 41332562, 2025). "Furthermore, compared with those in the shControl infection group, the levels of IL‐6 and TNF‐α in the cell supernatant from the Poly‐IC with TRIF‐knockdown group were increased." (PMID 40406905, 2025).
infection (continued). "Tumor necrosis factor-α (TNF-α) is a pivotal early mediator that recruits inflammatory cells to sites of infection; it activates neutrophils and lymphocytes, modulates tissue metabolism, and stimulates the release of other cytokines (e.g., IL-6 and IL-1β), acting synergistically in pain signaling." (PMID 41354715, 2025). "This study aims to examine the peripheral blood levels of TNF-α, IL-6, and IFN-γ in DFI patients and analyze their relationship with infection severity and prognosis, thereby offering diagnostic evidence for the early identification and personalized treatment of DFI." (PMID 40677522, 2025). "The production of infection may be related to the suppression of TNF-α, which can diminish cell death and depress proper immune responses during microbial infections." (PMID 40371340, 2025). "Additionally, Th1 cells produce TNF-α to promote macrophage phagosome–lysosomal fusion, apoptosis, and recruitment of immune cells to the site of infection." (PMID 40001899, 2025). "In addition, immune-related gene (IgM, IgT, and TNF-α) expression levels increased after infection with I. multifiliis." (PMID 40284708, 2025). "Although the precise mechanisms underlying CHIKV-induced AIN remain incompletely understood, existing evidence implicates an excessive inflammatory response, particularly the upregulation of pro-inflammatory cytokines such as IL-1β, IL-6 and TNF-α during the acute phase of infection." (PMID 40766840, 2025). "When the body is stimulated by MP infection, activated immune cells (such as macrophage and monocyte) release interleukin-6 (IL-6), interleukin-1β (IL-1β), and tumor necrosis factor-α (TNF-α), and these inflammatory factors reach the liver through blood circulation." (PMID 40171163, 2025). "Consequently, plotting mean scaled expression of CD38 and TNF in infection-induced expanded clusters against age revealed significant correlations." (PMID 40834853, 2025). "In addition, patients on long-term immunosuppressive therapies including oral prednisone and anti-TNF therapy show higher risks of Mab infections." (PMID 40415550, 2025). "The results regarding the levels of cytokines studied in this work (IL-1β, IL-6, TNF-α) may suggest that the presence of intracellular C. trachomatis in the infection will play a dominant role in the immune system response." (PMID 40647668, 2025). "Moreover, TNF-α, an important pro-inflammatory cytokine, reflects the host’s inflammatory response mechanisms triggered during infection." (PMID 40284708, 2025). "The weights of IFN-γ and TNF-α in PC2′ (Th1 markers) may represent a host attempt to control infection by increasing macrophage killing in response to local activation of the Th1 response." (PMID 41425969, 2025). "Additionally, co-infections involving IAV and SARS-CoV-2 exhibited cytokine dynamics dependent on the infection sequence, with elevated TNF-α, IL-6, and IFN-β levels following sequential infections, particularly when SARS-CoV-2 preceded IAV." (PMID 40005506, 2025). "It has been claimed that direct viral invasion into muscle tissue, myotoxic cytokines (such as TNF-alpha) secreted in response to infection and immunological responses secondary to infection may be responsible for muscle damage." (PMID 40324245, 2025). "Moreover, PEGylated phages effectively suppressed infection-driven cytokines, reducing IL-6, TNF-α, IFN-γ, and IL-1β levels toward baseline while inducing weaker IgG responses." (PMID 41309396, 2025). "When bacterial invasion activates intracellular NF-κB/MAPK signaling pathways, CDK9 is rapidly recruited to the promoter regions of immune genes, initiating the transcription of TNF-α, IL-6, and IL-1β genes and guiding immune cell migration to the infection site." (PMID 41515060, 2025). "The inhibition of IFN-γ and TNF production by MAIT cells could also conceivably aid the virus in establishing infection, as these cytokines are important in controlling HSV-1 infection." (PMID 40135871, 2025).
infection (continued). "Notably, TNF mRNA induction was enhanced as early as 3 h post-infection, with a corresponding increase in secreted TNF observed after 20 h of HMPV infection." (PMID 41346628, 2025). "Studies have shown that dysregulated proinflammatory cytokines such as IFNs, IL6, and TNF may compromise viral clearance while minimizing tissue damage, creating a condition that supports persistent infection despite low infectivity." (PMID 40649996, 2025). "TNF may have conflicting roles in the immune system, having the ability to induce inflammatory processes as well as fight infections and provide immunity against pathogens." (PMID 40650157, 2025). "Our results for the TNF-α analysis in PCOS patients showed a distinct increase of this proinflammatory cytokine in infections with atypical pathogens, and in particular the highest values were observed in the presence of C. trachomatis compared to the control groups." (PMID 40647668, 2025). "Furthermore, IFN-α, IFN-γ, and TNF-α show a trend toward being increased during recovery from infection." (PMID 39610883, 2025). "However, TNF-alpha inhibitors must be used with extreme caution, as they can reactivate latent TB or exacerbate an active one, given the essential role of TNF-alpha in macrophage activation and granuloma formation, essential for infection control." (PMID 40310305, 2025). "Therefore, TNFα appears to play an important role in inflammation and early defense against infections in the starry flounder, with its tissue-specific expression representing a strategic mechanism for localized immune responses." (PMID 40723580, 2025). "This may be due to immune activation from infection, which triggers the release of cytokines such as tumor necrosis factor, interleukin-1, gamma-interferon, and beta-interferon." (PMID 40315206, 2025). "Notably, the expression of TLR2 and TLR4 on ECs can be modulated in response to infection and inflammatory stimuli, either directly through exposure to lipopolysaccharide (LPS) or indirectly through cytokines such as TNF-α and interferon-gamma (IFN-γ)." (PMID 41268545, 2025). "In addition, the immune response activated by the chicken’s body to fight the infection produced proinflammatory cytokines, such as interleukin-1 (IL-1) and tumor necrosis factor-alpha (TNF-α), which were known to suppress appetite regulation." (PMID 40506037, 2025). "Furthermore, we showed that infection with T209L DENV of THP-1 macrophages led to reduced TNFα levels compared to WT infection." (PMID 40962941, 2025). "Second, TNF may play a larger role during Mab control in mice compared to IFNγ, which is different from infections with Mtb." (PMID 40415550, 2025). "Therefore, it is possible that the ability of the ST-J1 strain to counteract host cell TNF during infection is compromised due to this missing decoy TNF receptor encoded by the full-length ORF151A." (PMID 40431669, 2025). "This implied that there is a higher rate of infection for the TNF-alpha inhibitor cohort." (PMID 41306173, 2025). "In a model in which mice started HFD 8 weeks before infection, plasma TNF-α levels, as well as its concentrations in the heart, were elevated in the acute phase of infection, while the measurements in AT were similar between acutely infected and uninfected mice on HFD." (PMID 40333112, 2025). "In a murine model of MRSA-induced PJI, VZZ-8 NPs exhibited robust antibacterial efficacy, concurrently suppressing local TNF-α and IL-6 expression, and preventing infection-induced osteolysis, highlighting their comprehensive therapeutic potential for PJI treatment." (PMID 41305340, 2025). "Additionally, HAdV encodes four proteins – E1B/19K and E3 proteins (14.7K, 10.4K, and 14.5K) – that counteract TNF-mediated cytolysis, further supporting immune evasion and prolonged infection." (PMID 40103806, 2025).